LEP (leptin)
Diseases named in the same sentence as LEP in open-access papers (continued):
Sharing a sentence is not in itself a finding about the gene and the disease.
placental insufficiency (4 papers, 2016 to 2025). Failure of the placenta to deliver an adequate supply of nutrients and oxygen to the fetus. "The suggested pathogenic mechanisms of ENG, LEP, and FLT1 related to placental insufficiency IUGR needs further validation in cell and/or animal model." (PMID 35090410, 2022). "Increased LEP levels, possibly reflective of the inflammatory state and placental insufficiency in PE, may impair the cytolytic function of CD56dim NK cells, hampering their role in placental and fetal development." (PMID 39967661, 2025). "Thus, ENG and LEP as biomarkers were detected and validated in the placental tissue from pregnancies complicated by placental insufficiency IUGR." (PMID 35090410, 2022). "This study identified and validated ENG and LEP as key genes in the placental tissue from pregnancies complicated by placental insufficiency IUGR, with the clinical signs of asymmetric growth, oligohydroamnions, and/or increased pulsatility index of the umbilical artery." (PMID 35090410, 2022). "Thus, overexpression of ENG (p = 0.03) and LEP (p = 0.03) was significantly related to placental insufficiency IUGR status." (PMID 35090410, 2022). "ENG, LEP, and FLT1 were identified as key genes related to placental insufficiency IUGR, Significantly higher expression of ENG and LEP at RNA level in this disease was validated reliable by three GEO datasets repeatedly." (PMID 35090410, 2022). "A holistic gene expression profile of placental insufficiency IUGR has been generated and the key genes ENG and LEP has potential to serve as circulating diagnosis biomarkers and therapeutic targets for placental insufficiency IUGR." (PMID 35090410, 2022). "The expression of genes ENG, LEP, and FLT1 were significantly upregulated in placental insufficiency IUGR." (PMID 35090410, 2022). "The key genes LEP and ENG have potential to serve as circulating diagnosis biomarkers and therapeutic targets for placental insufficiency IUGR." (PMID 35090410, 2022). "The occurrence of placental insufficiency IUGR has been reported to be correlated with activation of genes such as TGFβ, NOD1, LEP." (PMID 35090410, 2022). "The LEP protein might be involved in cell cycle regulation by activating signaling pathways such as JAK2STAT3, MAPK1/3, or PI3K-AKT1 (consistent with a predicted pathway in the part of PPI analysis), further functions in pathogenesis of placental insufficiency IUGR." (PMID 35090410, 2022).
pregnancy induced hypertension (4 papers, 2012 to 2023). "Higher circulating leptin and the AA genotype of −2548 G/A polymorphism of the LEP gene may be associated with PE/pregnancy-induced hypertension." (PMID 37635936, 2023). "Leptin is known to be elevated in pre-eclampsia/ pregnancy induced hypertension (PE/PIH)." (PMID 22713493, 2012).
psychological distress (4 papers, 2014 to 2025). "Evidence from endocrinology and neurobiology further supports this view, as dysregulation of the hypothalamic–pituitary–adrenal (HPA) axis and altered leptin signaling have been associated with emotional dysregulation and affective symptoms." (PMID 40508907, 2025).
rectal cancer (4 papers, 2012 to 2021). A primary or metastatic malignant neoplasm that affects the rectum. "Taking into consideration the high variability of literature data, we wanted to check the modifications of leptin and adiponectin secretion exclusively in rectal cancer, which is often diagnosed in pre-metastatic stages and has a higher survival rate." (PMID 31425509, 2019). "Females with colon/rectal cancer had comparable leptin concentrations (6.3 ng/ml vs. 9.2 ng/ml; p=0.591)." (PMID 23173608, 2012).
renal dysfunction (4 papers, 2021 to 2025). "The available data indicate that the increased concentration of leptin in the blood of CKD patients may result from both decreased leptin elimination from the circulation by the kidneys (due to renal dysfunction) and increased leptin production by the adipose tissue." (PMID 33925217, 2021).
Rett syndrome (4 papers, 2009 to 2026). A severe neurodevelopmental disorder affecting the central nervous system. "In the Rett syndrome, raised circulating leptin levels and overactivity of the sympathetic nervous system are pathophysiological features of this genetic neurodevelopmental disorder." (PMID 19566930, 2009).
secondary hyperparathyroidism (4 papers, 2012 to 2021). Overproduction of parathyroid hormone in response to influence external to the parathyroid glands. "Adipocyte leptin expression and production was relatively reduced in case of severe secondary hyperparathyroidism and increased after parathyroidectomy." (PMID 34422722, 2021). "In subjects with trochanteric HF this complication was predicted by a history of CAD, secondary hyperparathyroidism and lower leptin levels." (PMID 22333003, 2012). "The independent predictors of in-hospital death were male sex, elevated PTH and lower leptin levels in patients with cervical HF, and secondary hyperparathyroidism in subjects with trochanteric HF." (PMID 22333003, 2012). "Additionally, PTH possibly blocks leptin secretion in case of severe secondary hyperparathyroidism." (PMID 34422722, 2021). "Conclusively, a positive loop between leptin and PTH is probably the case in primary hyperparathyroidism, whereas PTH seems to inhibit leptin expression in severe secondary hyperparathyroidism." (PMID 34422722, 2021). "Nevertheless, a negative feedback effect of PTH on leptin secretion was proposed in case of secondary hyperparathyroidism." (PMID 34422722, 2021). "In detail, serum leptin was negatively correlated to PTH in three clinical studies including 46, 73, and 161 hemodialysis patients, respectively, confirming the negative impact of secondary hyperparathyroidism on leptin secretion remarked in experimental studies." (PMID 34422722, 2021).
Sjögren syndrome (4 papers, 2010 to 2022). "detected an increasing MIP-1b expression of the ocular surface in DED patients, especially in Sjogren syndrome (SS) patients; however, no studies of increasing leptin or NCAM-1 in DED patients have been reported." (PMID 36419616, 2022).
thalassemia (4 papers, 2013 to 2022). An inherited blood disorder characterized by a decreased synthesis of one of the polypeptide chains that form hemoglobin. "In our study leptin resulted decreased in patients with the more severe form of thalassemia (TM) with respect to healthy subjects, indicating the impact of genotype and poly-transfusions in this alteration." (PMID 36699704, 2022). "This study aimed to assess the relationship between levels of leptin and troponin serums in patients with major thalassemia." (PMID 25914798, 2015). "The results of this study demonstrated that in patients with major thalassemia, there was significant correlation between serum leptin level and thyroxin hormone." (PMID 24575288, 2013). "On the other hand, in thalassemia patients also observed aspect a reduction in leptin partly due to the genetic defect This possibility is suggested that TNF and IL6 affect leptin much more than pituitary- hypothalamus axis." (PMID 24575288, 2013). "Body Mass Index (BMI ) were meuseurd in all patients and then, after collecting the samples, leptin and thyroid hormones levels of the serum were measured in the patients with thalassemia via ELISA method." (PMID 24575288, 2013). "In children with ß-thalassemia, fat cells are not able to synthesize adequate amounts of leptin and therefore, leptin starts to decrease." (PMID 25914798, 2015). "Perrone fin dines showed that in thalassemia patients, adipose tissue is not able to guarantee adequate leptin production just when the highest leptin secretion is needed and Perrone suggested that this inadequate leptin secretion may be a multi cause of the unbalanced in pubertal timing." (PMID 25914798, 2015).
thyroid hormone resistance (4 papers, 2012 to 2024). "Thus, the combined effect of peripheral thyroid hormone resistance and central leptin regulation increases TSH in plasma and has detrimental impacts on organs beyond the thyroid." (PMID 38352711, 2024). "One way in which weight gain could lead to an increase in serum TSH levels and, subsequently, thyroid hormone levels, is through the stimulatory effect of leptin, an adipose tissue-derived hormone, on thyrotropin-releasing hormone (TRH) or by decreasing thyroid hormone resistance." (PMID 22511976, 2012).
-dependent (3 papers, 2015 to 2020). "Moreover, the partial correlational analysis showed that the AUQ scores of the alcohol-dependent patients were positively correlated with the plasma leptin levels (r = 0.613, P < 0.001), rather than nesfatin-1 (r = 0.066, P = 0.569) after controlling for age as covariate." (PMID 32265847, 2020).
alopecia areata (3 papers, 2021 to 2025). Loss of scalp and body hair involving microscopically inflammatory patchy areas. "Nevertheless, recent research continues to investigate the possible link between alopecia areata and adipokines, especially adiponectin and leptin." (PMID 39852208, 2025). "The aim of the study was to evaluate the serum level of adiponectin, resistin and leptin in patients with alopecia areata in comparison to healthy controls." (PMID 34226603, 2021).
aneurysm (3 papers, 2021 to 2022). Bulging or ballooning in an area of an artery secondary to arterial wall weakening. "Pro-inflammatory cytokines such as resistin, leptin, and TNFα have been shown to induce changes leading to the formation of aneurysms, while adiponectin is the only known compound that is secreted by adipose tissue and limits the development of aneurysms." (PMID 35745168, 2022). "Intragroup analysis for group 2 showed increased Pecam-1, CXCL8, resistin, osteopontin and decreased levels of leptin, pentraxin-3 in KD with aneurysms as compared to patients without CAA (non-significant)." (PMID 36096831, 2022). "Intragroup analysis for group 3 patients revealed elevated VEGF-A, CXCL8, Leptin, Pentraxin-3, resistin in patients with CAA as compared to KD without aneurysms while pecam-1, endoglin and osteopontin were comparable in both." (PMID 36096831, 2022).
ankylosing spondylitis (3 papers, 2017 to 2023). An autoimmune chronic inflammatory disorder characterized by inflammation in the vertebral joints of the spine and sacroiliac joints. "One study showed that low leptin levels were associated with clinical improvement, assessed by Ankylosing Spondylitis Disease Activity Score (ASDAS) in axSpA patients treated with anti-tumor necrosing factor injections (TNFi)." (PMID 37559026, 2023). "Serum leptin correlated with the Bath Ankylosing Spondylitis Disease Activity Index (BASDAI), a validated patient-reported index of disease activity, and with acute-phase reactants (CRP, IL-6)." (PMID 36831072, 2023).
aortic aneurysm (3 papers, 2012 to 2023). A ruptured aneurysm located in the wall of the proximal portion of the descending aorta proceeding from the arch of the aorta. "Using aortic aneurysm models in mice we demonstrated that locally expressed leptin in the aortic wall promotes medial degeneration, which leads to aneurysm formation." (PMID 35015765, 2022). "Subsequently, we succeeded in rescuing aortic wall integrity and prevented the development of aortic aneurysm by counteracting local leptin activity, using peri-aortic application of a potent leptin antagonist." (PMID 35015765, 2022).
aortic valve stenosis (3 papers, 2024 to 2025). Aortic valve stenosis (AVS) is a condition characterized by narrowing of the heart's aortic valve opening. "In patients with aortic valve stenosis, the highest leptin production was found in SAT." (PMID 41226064, 2025). "Our objectives included examining the association between FCAVD and either a reduction in adiponectin or an increase in leptin levels across studies involving patients with various stages of FCAVD, ranging from aortic valve sclerosis to severe aortic valve stenosis." (PMID 39335491, 2024).
Apnea (3 papers, 2021 to 2023). Lack of breathing with no movement of the respiratory muscles and no exchange of air in the lungs. "Among the adipokines studied, leptin emerges as being most closely related to the severity of apnea, while the levels of IL-6, ET-1, and resistin are elevated during AMI regardless of OSA’s presence." (PMID 37834123, 2023).
atopic asthma (3 papers, 2018 to 2025). An asthma that is characterized by symptoms that are triggered by an allergic reaction caused by inhaled allergens such as dust mite allergen, pet dander, pollen and mold. "Our results confirmed previous association of the same LEP variant with atopic asthma in an independent cohort of pediatric patients." (PMID 30203371, 2018). "Higher leptin values were observed in non-atopic compared with atopic asthma patients (NOA + OA) [median (25th–75th) 4639 (2824–7425) pg/mL, 2859 (1471–4155) pg/mL, respectively; p = 0.041]." (PMID 35807067, 2022).
atrophic gastritis (3 papers, 2016 to 2025). "The significance of this study lies in the potential and invaluable use of leptin and ObR as biomarkers or as new therapeutic targets for the diagnosis and treatment of atrophic gastritis." (PMID 26839577, 2016). "We found that HFD feeding triggers leptin production and the activation of leptin-ObR signaling in the gastric mucosa, promoting atrophic gastritis and intestinal metaplasia." (PMID 26839577, 2016). "In this study, we show that diet-induced obese WT mice exhibit overexpression of leptin and activation of leptin receptor signaling in the gastric mucosa, leading to atrophic gastritis with intestinal metaplasia of the gastric mucosa." (PMID 26839577, 2016). "In this study, we showed that HFD feeding induces Cdx2 and Muc2 expression associated with increased leptin levels, suggesting the possibility that leptin acts to suppress cellular protection against gastric mucosal malignancies in the early stage of atrophic gastritis." (PMID 26839577, 2016).
bacteremia (3 papers, 2016 to 2024). "Similarly, the increased prevalence of adipokines, such as Leptin, in patients with COPD obesity has been shown to promote the shift of CD4+ T cells to Th1 cells, which may improve macrophage phagocytosis, bacterial clearance and reduce the incidence of bacteremia." (PMID 39450126, 2024).
Behçet's disease (3 papers, 2007 to 2019). "In Behçet's syndrome, apart from the role of leptin in inflammation, leptin also enhances the release of nitric oxide from endothelial cells and is involved in the pathophysiology of vascular lesions." (PMID 31824416, 2019). "Leptin levels in 35patients with Behçet's disease were also found to be higher than in healthycontrols in that study." (PMID 17641728, 2007). "A correlation between leptin levels and disease activity inpatients with Behçet's disease has been reported." (PMID 17641728, 2007). "There was a significant difference between the patients with Behçet's disease and control group for both log leptin (P = .000) and log CRP (P = .031)." (PMID 17641728, 2007). "There was a significant difference between the patients with Behçet's disease and control group for both logarithm of leptin (P = .000) and logarithm of CRP (P = .031)." (PMID 17641728, 2007). "In patients with Behçet's disease, log leptin was correlated with BMI (r = .44, P = .001), and α1-antitrypsin was correlated with log CRP (r = .61, P = .000)." (PMID 17641728, 2007). "However, studies that have been performed in other forms of systemic vasculitis (including Henoch-Schönlein purpura and Behcet's disease) have shown increased levels of leptin in active disease periods." (PMID 23259466, 2012). "In conclusion, the higher serumleptin levels in patients with Behçet's disease compared to control subjects in the present study might be attributed to a possible role for leptin in thepathogenesis of Behçet's disease." (PMID 17641728, 2007). "Future studies would be useful to clarify the potential influence of leptin in Behçet's disease." (PMID 17641728, 2007). "Leptin might have a possible role in the pathogenesis of Behçet's disease." (PMID 17641728, 2007). "Log leptin in nonocular Behçet's patients was significantly higher compared to its level inocular Behçet's disease and controls (P = .009)." (PMID 17641728, 2007). "In our study, patients with Behçet's disease with or without ocularinvolvement were found to have higher serum leptin and CRP levelscompared according to age-, sex-, and BMI-matched controls." (PMID 17641728, 2007). "Log leptin was not different between patients with ocular and nonocular Behçet's disease." (PMID 17641728, 2007). "In patients with nonocular Behçet's disease, α1-antitrypsin was correlated with log CRP (r = .56, P = .002), and log leptin was correlated with BMI (r = .052, P = .004)." (PMID 17641728, 2007).
bone cancer (3 papers, 2016 to 2024). A primary or metastatic malignant neoplasm affecting the bone or articular cartilage. "Despite several reports on IGF1, Rankl, leptin and the cytokine IL-8, the molecular signaling linking bone marrow adipocyte and bone tumor growth remains to be fully elucidated." (PMID 27049717, 2016). "The top upstream regulators in the bone cancer pain model are shown inFigure 8A (p-value of overlap <0.05, ANOVA) and includes cytokine IFNG (activation z-score 1.9); growth factor LEP (activation z-score 0.4); and transcription regulator NFE2L2 (activation z-score 1.9)." (PMID 30079380, 2018).
bone metastasis (3 papers, 2020 to 2024). Transfer of a neoplasm from its primary site to bones. "The correlation of the expression of leptin and its receptor with bone metastasis has been reported in pulmonary adenocarcinoma patients." (PMID 33804101, 2021).
brain injury (3 papers, 2015 to 2025). Acute and chronic (see also brain INJURIES, CHRONIC) injuries to the brain, including the cerebral hemispheres, CEREBELLUM, and brain STEM. "Adipokines, particularly leptin and adiponectin, are hormones secreted by adipose tissue and are emerging as key mediators in the pathophysiology of traumatic brain injuries." (PMID 40725107, 2025). "Leptin and IL-1beta treatment improves neuronal density and decreases apoptosis in the newborn rat and experimental animals with hypoxic-ischemic brain injury." (PMID 26629481, 2015). "Leptin has been suggested as a new biomarker predictive of the severity or outcome of brain injury." (PMID 40725107, 2025). "On the other hand, ICV injection of S1P into mice reduces food intake via JAK2/STAT3 dependent signaling, signaling molecules being also involved in leptin action and may act neuroprotective in brain injury." (PMID 33946318, 2021).